IGF1 (insulin like growth factor 1)
Diseases named in the same sentence as IGF1 in open-access papers (continued):
Sharing a sentence is not in itself a finding about the gene and the disease.
tumor (continued). "The connection to vessel formation becomes even more understandable when considering the synergistic collaboration of IGF-1 and VEGF in tumour neoangiogenesis." (PMID 24967356, 2014). "The levels of hepatic IGF-1 were analyzed in a further cohort of 29 HCC patients from whom tumor and adjacent non-tumor tissues were collected." (PMID 24586785, 2014). "Binding of IGF-1 to receptor IGF1R activates the pathway and enhances tumor development by stimulating cell proliferation and inhibiting apoptosis." (PMID 25006674, 2014). "In the present case, the mRNA expression of both IGF1 and IGF2 has increased (FDR = 4.65E-35 and FDR = 3.46E-15, respectively); however, the expression of IGF1R remained the same in the tumour tissue compared to that in the control tissue." (PMID 25496518, 2014). "Moreover, long term exposure to GH and insulin-like growth factor (IGF)-1 could induce proliferative capacity and increases the likelihood of developing malignancies, colorectal cancer being the most frequently observed neoplasm in acromegalic patients." (PMID 25127456, 2014). "Kasebet alshowed thatpatients with low IGF-1 levels were more likely to exhibit advanced pathologic parameters of HCC, such as multinodularity, large tumor size, and vascular invasion, and had shorter OS." (PMID 24595361, 2014). "The decrease in these proteins leads to higher circulating concentrations of free or bioactive insulin-like growth factor 1 (IGF-1) and a change in cell environment that stimulates tumor growth and inhibits apoptosis." (PMID 24587258, 2014). "After IGF1R binding to its ligand IGF1, two signal transduction pathways are activated: phosphatidylinositol-3 kinase (PI3K)/Akt and MAPK, and play important roles in tumour cell proliferation, differentiation and inhibition of apoptosis." (PMID 23998897, 2013). "Growth factors such as IGF1 and IGF2 drive HIF-1α through MEK1 and MEK2 signaling, that influences tumor glucolytic activity." (PMID 22875335, 2013). "Thus, attenuated RORC expression was correlated with a blunted tumor size- and IGF-1 reduction in patients treated with SA, indicating that these analogs may adversely affect clinical recovery in the presence of EMT progression (i.e., low E-cadherin) involving RORC-mediated mechanisms." (PMID 23825587, 2013). "The protein profiles of nine targets, namely IGFBP2, IGF1, SHKBP1, ETS1, IL1α, STX2, MAML3, EGR3 and XIAP were verified as significant contributors to tumor classification." (PMID 24282616, 2013). "Specifically, insulin-like growth factor 1 (IGF-1), transforming growth factor beta (TGF-β), and interleukin 6 (IL-6) secreted by astrocytes have been shown to promote proliferation of tumor cells in the brain." (PMID 24133630, 2013). "Pre-clinical studies have demonstrated that dalotuzumab acts by inhibiting IGF-1- and IGF-2-mediated tumor cell proliferation, IGF-1R autophosphorylation, and Akt phosphorylation." (PMID 23525758, 2013). "We also examined the functionality of the IR and IGF-1Rs in the tumor allografts by Western blotting for kinases in the PI3K signalling pathway in tumor tissue collected 1 h after sc administration of HI, X10 or IGF-1." (PMID 24260289, 2013). "The active HIF will mediate activation of multiple genes involved in angiogenesis (e.g., VEGF), cell survival (e.g., IGF-1), and metastasis (e.g., LOX and PAI-1) and this drives tumour progression." (PMID 23690850, 2013). "The most important findings suggested that IGF1, IL1α, SHKBP1, and EGR3 were able to distinguish between controls and primary tumor-bearing patients." (PMID 24282616, 2013).
tumor (continued). "The tumor endometrium expressed significantly lower levels of IGF-1, IGF-1R, and IGF-2, and significantly higher levels of IGF-2R and IGFBP-3, compared with tumor-adjacent endometrium (p < 0.05)." (PMID 22720981, 2012). "It was found that expression of IGF1, HGF, PDGFC, and PDGFD were significantly increased 5.32-, 10.21-, 6.24-, and 3.24-fold in tumor tissues, respectively, when compared with arachnoidal tissue by qRT-PCR." (PMID 23285163, 2012). "We tested the expression of IGF-1, IGF-1R, IGF-2, IGF-2R, IGFBP-3, ERα and ERβ mRNA on 58 tumor tissue samples and 31 tumor-adjacent endometrial tissue samples from patients with EAC and 42 normal endometrial tissue samples, using RT-PCR." (PMID 22720981, 2012). "We plotted baseline levels of IGF-1 or IGFBP-3, and maximum percent tumor reduction, time to progression, maximum proportional changes in neutrophil or platelet counts, AUC of ganitumab, minimum observed concentration, Cmax, or t1/2, z (data not shown)." (PMID 22810805, 2012). "Proving the importance of studying the benefits of survival factors in MM in a syngeneic environment, IGF-1 was in this model found to induce VEGF production and angiogenesis and was certainly proving important for tumor growth." (PMID 22348393, 2012). "In the tumor group, IGF-1 and IGF-2 levels were strongly correlated with ERα expression (r = 0.6439 for IGF-1, r = 0.5228 for IGF-2), and were weakly correlated with ERβ expression (r = 0.4155 for IGF-1, r = 0.3555 for IGF-2)." (PMID 22720981, 2012). "We further study the correlation of IGF-1, IGF-1R, IGF-2, IGF-2R, and IGFBP-3 mRNA expression with ERα and ERβ mRNA expression in tumor, tumor-adjacent and control endometria." (PMID 22720981, 2012). "The mRNA level of IGF-1, IGF-1R, IGF-2, IGF-2R, and IGFBP-3 was significantly higher in tumor and tumor-adjacent endometrium than that in control endometrium (p < 0.05)." (PMID 22720981, 2012). "IGFBP-3 can therefore reduce IGF-1 bioavailability and inhibit IGF-1 interaction with the IGF-1 receptor, thereby functioning as a tumor suppressor." (PMID 22879989, 2012). "Both naïve and tumor-educated macrophages produced significantly more IGF-1 after IL-4 treatment; tumor-educated macrophages more than doubled IGF-1 output compared to naïve samples (green bars)." (PMID 21699731, 2011). "IGFBP-7, although has relatively low affinity toward IGF-1 and IGF-2, exerts a similar anti-tumor effect as its high affinity IGFBP counterpart IGFBP-3." (PMID 21729319, 2011). "In summary, all these studies indicate that insulin, IGF-1, IGF-2, and their signalingvia the IR and IGF-1R can induce tumor growth." (PMID 23908801, 2011). "Second, high insulin and insulin-like growth factor (IGF)-1 levels resulting from chronic ingestion of CHO-rich Western diet meals, can directly promote tumor cell proliferation via the insulin/IGF1 signaling pathway." (PMID 22029671, 2011). "It is becoming increasingly evident that the Type-1 insulin-like growth factor (IGF-1R) and its ligands (IGF-1, IGF-2) play roles in both tumor cell proliferation and survival, and proliferation of vascular endothelial cells." (PMID 21197468, 2011). "Animal models have shown decreased tumor growth after IGF1R inactivation and with decreased circulating or tissue levels of IGF1." (PMID 21696633, 2011). "Five miRNAs (19b, 29a, 29b, 29c and 148a) shared 70 predicted targets, some of which (CDK6, PTEN, IGF1, FRS2, PDGFRA, PIK3R1 and MXD1) regulate cellular proliferation and tumor suppression." (PMID 20949028, 2010). "Our analysis of differential expression between adjacent stroma and tumor epithelia showed that the cytokines, CCL5 and CXCL 13, and the growth factors, IGF-1 and FGF-2, were upregulated in stromal cells." (PMID 20426842, 2010). "Based on this communication, inter-relationships among AKR1C3, ER, IGF-1, Akt, and subsequent VEGF expression deserve further investigation for tumor angiogenesis and progression." (PMID 21134280, 2010).
tumor (continued). "Although many growth factors regulate the angiogenic response in the tumour microenvironment, we will focus our discussion on vascular endothelial growth factor (VEGF) and insulin-like growth factor-1 (IGF-1)." (PMID 18182993, 2008). "Yet, gene expression of insulin-like growth factor-1 (IGF-1), a potent anabolic hormone, was down-regulated in skeletal muscles from tumor bearing rats." (PMID 17678552, 2007). "The higher expression of IGF1, BCL2, and CCND1 in the BEST prognosis group was unanticipated, as these genes are commonly considered to be tumor- promoting genes." (PMID 17206280, 2007). "Tumor cell growth in response to growth factors, such as Heregulin (HRG), epidermal growth factor (EGF), or insulin-like growth factor-1 (IGF-1), was also studied." (PMID 16168116, 2005). "Since plasma glucose levels are predictive of both tumour growth and IGF-1 levels, we next analysed the relationship between plasma IGF-1 levels and CT-2A tumour growth." (PMID 14520474, 2003). "This approach highlighted several putative iCAF-enriched populations from both normal and tumour samples; in normal tissues these included Stress-response Fib, CXCL8 + Breast Fib and universal (PI16+) fibroblasts; in tumours, IL11 + CAF, IGF1 + CAF and proto-CAF." (PMID 39757146, 2025). "Additionally, insulin growth factor-1 (IGF-1)-dependent activation of the AGER signaling in adjacent endothelial cells fuels angiocrine mechanisms and tumor progression." (PMID 40647480, 2025). "Additionally, macrophage-derived IGF-1 activates IGF-1R and PI3K signaling pathways in tumor cells, which promote tumor recurrence following CSF-1R inhibition." (PMID 40076738, 2025). "I consider cabergoline treatment as first line post-surgery for any symptomatic patient with above normal IGF-1(≥1.5–2 ULN) when there is no visible residual tumor on MRI." (PMID 40575269, 2025). "This association is particularly strong for ER+ tumors, irrespective of menopausal status, suggesting that IGF-1 synergizes with estrogen receptor signaling to drive tumor initiation and progression." (PMID 41157306, 2025). "Downregulation of CSF-1 in GBM cells by fibulin-3 inhibition did not lead to increased IGF-1 in the tumor, possibly preventing this tumor-salvage pathway." (PMID 40844085, 2025). "IGF‐1, a potent mitogen, promotes cell proliferation and survival while inhibiting apoptosis via PI3K/AKT/mammalian target of rapamycin (mTOR) and MAPK pathways, fostering tumor initiation and progression." (PMID 41267926, 2025). "Beyond remodeling, CAFs also secrete a broad range of growth factors, including hepatocyte growth factor (HGF), fibroblast growth factor (FGF), insulin-like growth factor 1 (IGF-1), and TGF-β, which drive tumor cell proliferation and induce epithelial-to-mesenchymal transition." (PMID 40871003, 2025). "Additionally, IGF‐1 and insulin can upregulate the expression of vascular endothelial growth factor (VEGF), increasing tumor angiogenesis and further promoting tumor growth." (PMID 40550558, 2025). "Beyond its relationship with IGF-1, the primary physiological function of IGFBP3 is to suppress cell proliferation and growth, a function that is exploited when used as a tumor-suppressive agent." (PMID 39886833, 2025). "Given that IGF1 and IGF1R can also be expressed by tumor cells and influence oncogenic processes both in GH-dependent and GH-independent manners, their expression levels may further complicate the assessment of the activity of the GH pathway in UC." (PMID 40806252, 2025). "For instance, SCFAs such as butyrate and propionate can epigenetically remodel prostate epithelial cells by inhibiting histone deacetylases, while dysbiotic enrichment of Ruminococcaceae and Bacteroides enhances IGF-1/PI3K/AKT signaling, promoting tumor cell survival." (PMID 41384118, 2025). "Additionally, hypoxia enhances IGF1-mediated VEGF expression, promoting angiogenesis and sustaining tumour growth." (PMID 39796756, 2025).
tumor (continued). "IGF-1 is known to promote the invasive and EMT process of tumors as well as tumor resistance." (PMID 40510161, 2025). "Additionally, it has been demonstrated that MSCs stimulate tumor angiogenesis by releasing bFGF, VEGF, FGF-2, IL-8, IL-6, IGF-1, TNF, and TGF β." (PMID 39974358, 2025). "Further growth factors, such as insulin like growth factor (IGF-1), epidermal growth factor (EGF) and TGFα might also present an autocrine action relevant for tumor proliferation, as their receptors are present in NEN." (PMID 40214893, 2025). "Postoperatively, IGF-1 levels declined from 495 to 240 ng/mL, and no residual tumor tissue was identified on follow-up MRI." (PMID 40842744, 2025). "I consider first-generation SSAs treatment post-surgery for any symptomatic patient with above normal IGF-1(≥1.5–2 ULN) when there is no visible residual tumor on MRI." (PMID 40575269, 2025). "The impact on the IGF-1 axis is more complex: while IGF-1 levels may increase, this is often accompanied by higher IGF-binding proteins, which can mitigate tumor-promoting effects." (PMID 41178954, 2025). "Furthermore, monitoring circulating tumor DNA for signs of emerging IGF1R pathway activation, along with serial plasma measurements of stromal IGF1, offers a promising non-invasive strategy for tracking disease progression." (PMID 41275311, 2025). "In TN BC, IGF-1 signaling is crucial for promoting cell proliferation and survival, largely by activating key pathways such as PI3K/AKT and MAPK, which support tumor growth and enable cells to resist apoptosis, underscoring its potential as a therapeutic target." (PMID 40894036, 2025). "Our findings also suggest that integrin dynamics modulate the IGF1-induced regulation of CYR61 in a cell line-specific manner, which may reflect distinct tumor phenotypes and therapeutic vulnerabilities." (PMID 41009559, 2025). "In contrast, the association between IGF-1 and incidence of NAFLD was not significantly modified by age, BMI and tumor function (P interactions > 0.05)." (PMID 38370349, 2024). "After carefully reviewing the current knowledge, the use of CRMs might be recommended when a particular pathway, such as PI3K/AKT/mTOR or IGF1/IGFBP, is upregulated in the tumor and can be modulated by the intervention." (PMID 39195514, 2024). "IGF-1 increases BRCA1 gene expression and enhances BRCA1 promoter activity, indicating a complex, bidirectional interplay between IGF-1 pathways and BRCA1-mediated tumor protective pathways." (PMID 39273251, 2024). "In addition to directly inhibiting tumor cell proliferation, GHRH antagonists reduce the secretion of growth factors such as IGF-1, VEGF, and pro-inflammatory cytokines, which are essential for tumor angiogenesis and metastasis." (PMID 39592529, 2024). "In addition, IGF1 mediates a conserved signal through Nrf2 for the induction of BNIP3, regulating the synthesis and turnover of mitochondria in tumor cells." (PMID 38892104, 2024). "Regarding the impact of biochemical control based on tumor size reduction, the literature speaks of this particularly in the scenario of recurrence, with the most frequent being the elevation of IGF-1 or GH, but not both." (PMID 39803157, 2024). "Paracrine signaling inhibitors, targeting paracrine factors like NLGN3, IGF‐1, and their downstream signaling pathways could disrupt the supportive TME for tumor cells." (PMID 39469896, 2024). "Significant correlations were recorded between MEG3 and anatomical site, SIRT1 and tumor stage, and miR-27a/IGFBP3 and LN metastasis among obese CRC patients, while IGF1 was correlated with tumor stage and LN metastasis among non-obese CRC patients." (PMID 38704452, 2024). "Circulating levels of GH, IGF-1, sex hormones, and THs may directly or indirectly affect the expression levels of IGF-1 and IGF-1R in tumor tissues.TC tends to be more aggressive in children and adolescents with higher GH and IGF-1 levels." (PMID 39104813, 2024).
tumor (continued). "Protein–protein interaction analysis suggested that IGFBP4 is associated with IGF1, IGF2, and extracellular matrix associated proteins such as COL4A2, which was a significant factor affecting tumor metastasis and implying that IGFBP4 affects cell invasion through the IGF signaling pathway." (PMID 37349627, 2024). "Additionally, tumour heterogeneity contributes to the variance in IGF‐2 secretion and metabolic impact, reflecting in the IGF‐2:IGF‐1 ratio." (PMID 38411039, 2024). "In adulthood, IGF-1 can potentially work as a mitogen factor, and IGF-2 may contribute to greater tumor aggression." (PMID 38612776, 2024). "In addition, IGF-1 secretion by osteoclasts was enhanced by CM of 5-8F and BM3 when osteoclasts were cultured in tumor cell CM." (PMID 38342894, 2024). "Metformin also has indirect antitumoral effects due to its ability to reduce insulin and insulin-like growth factor 1 (IGF-1) levels and to influence metabolic pathways such as lipid metabolism and inflammation, which are known to promote HCC tumour growth and proliferation." (PMID 38668314, 2024). "Nonetheless, the effect of CR in reducing tumor burden persists, suggesting a possible non-IGF-1 mediated response or a reduction in tumor and peritumoral expression of IGF-1 or IGF1R." (PMID 39195514, 2024). "During liver carcinogenesis, the secretion of IGF1 by adjacent hepatocytes may lead to paracrine stimulation of HCC and more aggressive tumor behavior." (PMID 39042294, 2024). "The IGF1 level was greater in adjacent nonneoplastic liver tissues than in tumor tissues, which was correlated with significantly worse survival after HCC resection." (PMID 39042294, 2024). "Sex and tumor size did not affect IGF-1 values at baseline while IGF-1 was significantly lower in overweight or obese than in normal-weight patients (median ± IQR 164.5 ± 139.0 ng/ml versus 132.0 ± 50.0 ng/ml, p = 0.04)." (PMID 38902646, 2024). "Consequently, antibodies and small molecules targeting IGF-1 and IGF1R have been developed and tested in pre-clinical and clinical models, showing the potential to delay tumor growth and increase sensibility to CT and RT." (PMID 39195514, 2024). "Additionally, neuronal activity can affect the behavior of tumor cells by releasing proteins such as brain‐derived neurotrophic factor (BDNF), NLGN3, and insulin‐like growth factor‐1 (IGF‐1) in the microenvironment." (PMID 39469896, 2024). "Moreover, Werner and Bruchim (2012) reviewed the interactions between IGF and BRCA1 signaling pathways, emphasizing the convergence of IGF1-mediated cell survival, proliferative pathways and BRCA1-mediated tumor suppressive pathways." (PMID 38612922, 2024). "Likewise, high IGF-1 levels activate the PI3K/AKT signaling and decrease apoptosis, which would increase tumor progression." (PMID 38164270, 2024). "RNA expression of GH, GHR, IGF1, IGF1R, and PRLR is also detected using qPCR, and IGF1 production in tumor cells is markedly lower in mouse tumor cells but not in human tumor cells." (PMID 39000545, 2024). "Rapamycin eliminated osteoclastic CM or recombinant IGF-1 induced phosphorylation of S6 in 5-8F, 5-8F OE and BM3 tumor cells, and when mTORC1 was inhibited, osteoclastic CM or recombinant IGF-1 failed to promote proliferation of 5-8F OE, and BM3 tumor cells." (PMID 38342894, 2024). "GH2h correlated with all parameters of biochemical control at 6 months of follow-up: GH (rs 0.51; p=0.001), IGF1-SDS (rs 0.43; p<0.01), and tumor volume (rs 0.74; p<0.001); and with the %ΔIGF1 (rs 0.36; p=0.01), the ΔGH% (rs 0.50; p<0.01), and the Δvolume% (rs 0.49; p=0.02)." (PMID 38027102, 2023). "IGF1 and IGF2 could influence tumor growth and metastatic process through their effect on cell proliferation, angiogenesis and the epithelial-to-mesenchymal transition (EMT)." (PMID 37373068, 2023).